SNORA73A (small nucleolar RNA, H/ACA box 73A)
Synonyms: U17A; E1-7; E1b; E1; RNE1; RNU17A
Gene: Small nucleolar RNA gene on chromosome 1 (28,507,366 to 28,507,571, forward strand). Ensembl gene ENSG00000274266.
Gene Ontology:
Biological process: RNA processing
Cellular component: nucleolus
Homologues: Orthologues: chimpanzee SNORA73 (97% identical), macaque SNORA73 (96% identical), dog SNORA73 (90% identical), guinea pig SNORA73 (86% identical). Paralogues in human: SNORA73B (93% identical), RNU105B (85% identical), RNU105C (82% identical), SNORA73 (81% identical), SNORA73 (80% identical), SNORA73 (74% identical), SNORA73 (39% identical).
Diseases named in the same sentence as SNORA73A in open-access papers:
SNORA73A is named in the same sentence as 4 diseases in open-access papers, as found by Europe PMC text mining. Sharing a sentence is not in itself a finding about the gene and the disease.
SNORA73A shares sentences with these, for which no sentence is quoted: colon cancer (1 paper); colorectal cancer (1); hepatocellular carcinoma (1); tumor (1).